HGF (hepatocyte growth factor)
Diseases named in the same sentence as HGF in open-access papers (continued):
Sharing a sentence is not in itself a finding about the gene and the disease.
diffuse large B-cell lymphoma (3 papers, 2008 to 2025). "HGF‐induced c‐Met activation in diffuse large B cell lymphoma (DLBCL) cells also leads to MEK‐dependent phosphorylation of the MAP kinases ERK1 and ERK2, which are associated with the regulation of cell proliferation." (PMID 34651428, 2021). "Similarly, in diffuse large B cell lymphoma (DLBCL), patients demonstrated increased HGF and c-MET in their blood, bone marrow, plasma, and pleural fluid, which correlates with clinic outcomes." (PMID 40520181, 2025).
dry eye (3 papers, 2018 to 2024). "The lacrimal lake, as observed on tear strips, appeared similar in both PEI2-GNP-naked vector and BMP7+HGF groups, suggesting that combination therapy with BMP7+HGF does not compromise tear production or invoke a dry eye condition." (PMID 29490341, 2018).
Erythema (3 papers, 2009 to 2025). Redness of the skin, caused by hyperemia of the capillaries in the lower layers of the skin. "HGF concentration of autistic children with GI disease was compared to GI disease severity (including LNH and erythema)." (PMID 20029653, 2009).
gastric ulcer (3 papers, 2010 to 2023). An ulcerated lesion in the mucosal surface of the stomach. "In addition, there are some recent studies showing an induction in the HGF expression synergistic with Cox-2 expression in the gastric ulcer healing process." (PMID 27942290, 2010).
gestational diabetes mellitus (3 papers, 2015 to 2024). "We investigated associations of serum hepatocyte growth factor (HGF) with risk of gestational diabetes mellitus (GDM)." (PMID 27158627, 2015). "The purpose of this study was to further evaluate the relationship of various protein markers, including prolactin, HGF, TNFα, TRAIL, PAI-1, RANKL, and OPG, with gestational diabetes in women." (PMID 30147996, 2018).
glomerulosclerosis (3 papers, 2012 to 2019). A hardening of the kidney glomerulus caused by scarring of the blood vessels. "TGF-β1 has been reported to contribute to cell hypertrophy and the increased synthesis of collagen, ultimately leading to glomerulosclerosis and tubule-interstitial injury during DN development, while HGF has been reported to ameliorate DN by blocking the profibrotic actions of TGF-β1." (PMID 31871464, 2019). "In addition, in this study, SHED downregulated the serum levels of TGF-β while increasing the serum levels of HGF, thereby preventing glomerulosclerosis and tubule-interstitial injury in DN." (PMID 31871464, 2019).
Hodgkins lymphoma (3 papers, 2016 to 2024). A heterogeneous group of malignant lymphoid neoplasms of B-cell origin characterized histologically by the presence of Hodgkin and Reed-Sternberg (HRS) cells in the vast majority of cases. "In the group of patients presenting a nodular sclerosis subtype, the immune profile switched at relapse, with an upregulation of LGALS1 and TGFB1 and downregulation of CD163, CD274, HGF, IL15, and ICOS." (PMID 36230815, 2022).
intraepithelial neoplasia (3 papers, 2013 to 2025). A precancerous neoplastic process that affects the squamous, glandular, or transitional cell epithelium without evidence of invasion. "Similar to human OSCC tissues, HGF was not expressed or was weakly expressed in normal oral mucosa of the Wt-control group but was upregulated in epithelial dysplasia and tumor tissues in the Wt-4NQO group." (PMID 34970484, 2021).
kidney (3 papers, 2017 to 2023). "It has been reported that HGF mRNA and HGF protein were expressed in renal interstitial cells, presumably endothelial cells and macrophages after ischemic kidney injury." (PMID 30845150, 2019). "It will be important to address in how far HGF-mediated fibroblast activation does also play a role in urogenital cancers." (PMID 28212658, 2017).
laryngeal carcinoma (3 papers, 2019 to 2023). Carcinoma that arises from the laryngeal epithelium. "Analogous phenomenon was noticed by Lee and co-workers who showed that ME22S (a novel EGFR/MET bispecific antibody) significantly inhibited HGF-stimulated migration and invasion of laryngeal carcinoma cells." (PMID 31649529, 2019).
laryngeal squamous cell carcinoma (3 papers, 2020 to 2025). A squamous cell carcinoma that arises from the larynx. "Serum HGF concentrations in patients with advanced and poorly differentiated laryngeal squamous cell carcinoma are significantly higher than those in patients with early stage and highly differentiated disease." (PMID 40823073, 2025). "Serum HGF concentrations are significantly higher in patients with advanced and poorly differentiated laryngeal squamous cell carcinoma than those with early and highly differentiated disease." (PMID 40823073, 2025).
leukocytosis (3 papers, 2015 to 2021). "In PV patients, high levels of IL-12 are associated with hematocrit; high IL-1β and HGF levels are associated with leukocytosis; low IL-6 and FGF (fibroblast growth factor) levels are associated with hemoglobin concentration; and low GM-CSF levels are associated with thrombocytosis." (PMID 34084749, 2021). "In PV, correlation of IL-1β, IL2, IL7, b-FGF, and HGF with leukocytosis has been described." (PMID 26525644, 2015).
meningioma (3 papers, 2021 to 2023). A generally slow growing tumor attached to the dura mater. "We investigated the association between curcumin, EMT, and HGF/c-MET in meningioma cells." (PMID 34408780, 2021). "Compared to WHO grade I meningioma tissues, expression levels of HGF and c-MET were found to be elevated in WHO grade III (malignant) meningioma tissues." (PMID 34408780, 2021). "To further investigate the effects of the PI3K/Akt/mTOR pathway on HGF-induced meningioma cells, we treated IOMM-Lee cells with a c-MET inhibitor (SU11274, 5 μmol/l) and a PI3K inhibitor (LY29400225, μmol/l), respectively, and then the proliferation, migration, invasion, and EMT were detected." (PMID 34408780, 2021). "Expressions of HGF and c-MET have been associated with aggressive meningiomas." (PMID 34408780, 2021). "In accordance with these results, curcumin inhibited HGF-induced EMT in meningioma cells." (PMID 34408780, 2021). "In addition, treatment of human malignant meningioma cells with the tyrosine protein kinase (c-MET) inhibitor (SU11274) or the phosphoinositide 3-kinase (PI3K) inhibitor (LY294002) suppressed HGF-induced migration and EMT." (PMID 34408780, 2021). "This study aimed at determining whether curcumin inhibits HGF-induced EMT of meningioma cells." (PMID 34408780, 2021). "Therefore, the results indicated that two inhibitors reversed HGF-induced EMT of meningioma cells." (PMID 34408780, 2021). "Therefore, curcumin inhibits HGF-induced EMT of meningioma cells." (PMID 34408780, 2021). "We found that curcumin blocks hepatocyte growth factor- (HGF-) induced proliferation, migration, invasion, and EMT of human malignant meningioma cells by regulating the PI3K/Akt/mTOR signaling pathway." (PMID 34408780, 2021). "Both HGF and c-MET were strongly positive in malignant meningioma tissues and weakly positive in benign meningioma tissues." (PMID 34408780, 2021). "In terms of tumour recurrence, lower TGF-ß expression and higher expression of OPN, HGF/SF, MIP and MMP-9 were found to correlate significantly with the recurrence of meningiomas." (PMID 34503077, 2021). "We found that HGF and c-MET levels were upregulated in malignant meningioma clinical tissues, compared to benign meningioma clinical tissues, consistent with previous studies." (PMID 34408780, 2021). "To detect the expression of HGF and c-MET in meningioma, we performed immunohistochemistry and western blot assays." (PMID 34408780, 2021). "Studies have reported that HGF is linearly correlated with the EMT process, and it accelerates tumorigenesis, including in meningioma." (PMID 34408780, 2021). "In addition, HGF and c-MET are overexpressed in meningioma and are predictive markers as well as targeted therapy molecules for meningioma." (PMID 34408780, 2021).
metastatic prostate carcinoma (3 papers, 2012 to 2022). A carcinoma that arises from the prostate gland and has spread to other anatomic sites. "HGF-activated STAT3 has been shown to link to the HGF/c-MET axis to stimulate the progression of metastatic prostate cancer." (PMID 35705962, 2022). "In the current study human metastatic prostate cancer PC-3 cells were found to overexpress not only c-Met but also HGF at the transcriptional level." (PMID 22639908, 2012).
non-alcoholic fatty liver disease (3 papers, 2023 to 2025). "They showed that serum levels of HGF were also elevated in non-alcoholic fatty liver disease (NASH)." (PMID 38202116, 2023).
osteoporosis (3 papers, 2020 to 2022). A condition of reduced bone mass, with decreased cortical thickness and a decrease in the number and size of the trabeculae of cancellous bone (but normal chemical composition), resulting in increased fracture incidence. "DPSCs or DPSCs‐HGF were injected intravenously into ovariectomy‐induced osteoporosis mice." (PMID 31943813, 2020). "Next, the efficacy of FGF2/HGF priming on the osteogenic potential of ADSCs from donors with chronic diseases will be widely evaluated, and its effect on bone defects will be confirmed using a non-clinical osteoporosis model." (PMID 35805126, 2022).
pressure ulcer (3 papers, 2015 to 2025). "Cell-based therapies using ASCs are highly efficacious for decubitus ulcers, reportedly reflecting the actions of angiogenenic factors, such as HGF and VEGF." (PMID 25884474, 2015). "We previously demonstrated that SHED-CM has potent therapeutic effects in a mouse model of the formation of pressure ulcer induced by cutaneous ischemia–reperfusion injury, which highly depend on antioxidative and angiogenic activities, mainly via HGF and VEGF." (PMID 39857443, 2025).
primary biliary cirrhosis (3 papers, 2006 to 2020). "HGF gene transfection effectively prevented the proteinuria and histopathological changes associated with glomerulonephritis, primary biliary cirrhosis and Sjogren's syndrome." (PMID 16859527, 2006). "HGF may represent a novel strategy for the treatment of systemic lupus erythematosus, Sjogren's syndrome and primary biliary cirrhosis." (PMID 16859527, 2006). "Therefore, HGF may represent a novel strategy for the treatment of systemic lupus erythematosus, primary biliary cirrhosis, and Sjogren's syndrome." (PMID 16859527, 2006).
proliferative vitreoretinopathy (3 papers, 2016 to 2019). Vitreoretinal membrane shrinkage or contraction secondary to the proliferation of primarily retinal pigment epithelial cells and glial cells, particularly fibrous astrocytes, followed by membrane formation. "Previous studies found that HGF is associated with proliferative diabetic retinopathy and proliferative vitreoretinopathy." (PMID 30665391, 2019).
promyelocytic leukemia (3 papers, 2015 to 2025). "Therefore, CM of MAD-NT cells, a HGF producing subclone of the promyelocytic leukemia cell line HL60, was used." (PMID 25884419, 2015). "Our results demonstrate that HGF increases NRP-1 expression by activating the transcription factor RARA, which is a component of the promyelocytic leukemia/RARA oncoprotein." (PMID 40419692, 2025).
retinal detachment (3 papers, 2016 to 2025). An eye emergency condition which may lead to blindness if left untreated. "Our decision to make this assessment stemmed from an earlier report in which it was shown in a mouse retinal detachment model that increases in vitreous chamber HGF/SF content are associated with c-Met upregulation and activation." (PMID 27936052, 2016). "The concentrations of three molecules out of six were higher than 1 ng/ml in all retinal detachment groups (median concentrations in PVR: HGF = 8.135 ng/mL, MCP-1 = 1.950 ng/mL, MIF = 4.371 ng/mL)." (PMID 32542038, 2020). "This is evident since in a retinal detachment mouse model increases in HGF/SF levels occur eliciting c-Met upregulation followed by increases in RPE migration." (PMID 27936052, 2016). "In addition, a report on cytokines in the subretinal fluid of patients with ROP with retinal detachment found that HGF was low and VEGF was high up to stage 4, when the detachment began, and that HGF and VEGF were at the same concentration at stage 5, when the detachment was extensive." (PMID 40075818, 2025). "Levels of HGF, IL-6, IL-8, IL-16, IFN-gamma, MCP-1, and MIF were significantly higher in all groups of retinal detachment compared to ERM." (PMID 32542038, 2020). "Levels of HGF (p<0.0001), IFN-gamma (p<0.0001), IL-6 (p<0.0001), IL-16 (p<0.0001), MIF (p<0.0001), MCP-1 (p<0.0001) were significantly higher in all groups of retinal detachment compared to the group of ERM." (PMID 32542038, 2020). "The concentrations of HGF, IFN-gamma, IL-6, IL-16, MIF, MCP-1 were significantly higher in all groups of retinal detachment compared to controls." (PMID 32542038, 2020).
seminoma (3 papers, 2019 to 2023). A radiosensitive malignant germ cell tumor found in the testis (especially undescended), and extragonadal sites (anterior mediastinum and pineal gland). "We also demonstrated that the non-seminoma cell line NT2D1 is the best responsive to the administration of exogenous HGF, with respect to TCam-2 and NCCIT cell lines." (PMID 37509533, 2023). "We studied c-MET and HGF expression even in seminoma and non-seminoma derived cell lines (TCam-2, NCCIT, NT2D1), demonstrating that HGF is not expressed by all these cell lines." (PMID 37509533, 2023). "Some of our previous studies investigated the c-MET/HGF system involvement in non-seminoma cell malignant behavior." (PMID 37509533, 2023). "Herein, we report the HGF immunoreactivity of samples from patients affected by seminoma (SE, four patients) or embryonal carcinoma (EC, two patients)." (PMID 33212946, 2020). "Immunohistochemical analysis of HGF reported herein clearly indicated that embryonal carcinoma samples have stronger immunoreactivity to HGF with respect to seminoma samples." (PMID 33212946, 2020). "In line with these clinical data, the non-seminoma derived NT2D1 cells exhibit the highest sensitivity to HGF administration: these cells respond to HGF increasing their malignant behaviour in terms of proliferation, chemo-attraction and invasiveness." (PMID 30646583, 2019). "Notably, in the same paper, we demonstrated that non-seminoma-derived NT2D1 cells respond to HGF administration, increasing their proliferative and migratory index." (PMID 33212946, 2020). "In the light of these results, we wondered whether there was a difference in testicular HGF availability in seminoma and embryonal carcinoma biopsies." (PMID 33212946, 2020). "Moreover, HGF immunoreactivity in seminoma samples is mainly localized to the cytosol of the cells, whereas in embryonal carcinoma, HGF appears to be distributed mainly outside the cells." (PMID 33212946, 2020). "In a recent paper we found that, HGF is able to stimulate the malignant and aggressive behaviour of NT2D1 non-seminoma cells, and that this phenomenon depends on c-MET activation." (PMID 30646583, 2019). "In the present study, we investigated the role of PI3K in the HGF-dependent and c-MET-activated malignant behavior of NT2D1 non-seminoma cells, studying the effects of PI3K inhibition on the already described biological responses to HGF (proliferation, migration, and invasion)." (PMID 33212946, 2020). "Moreover, the results herein reported strongly stimulates to investigate deeply, at proteomic level, the overexpression of HGF as well the over-activation of c-MET and c-Src in TGTCs biopsies with special focus on non-seminoma lesions." (PMID 30646583, 2019).
acinar prostatic adenocarcinomas (2 papers, 2015 to 2022). "Our published studies have shown that FYN plays an important role in cellular motility in cancer, particularly when driven by hepatocyte growth factor (HGF), which is found in abundance in the plasma of patients with both acinar prostatic adenocarcinomas and NEPC." (PMID 26624980, 2015).
Acute hepatic failure (2 papers, 2012 to 2013). "Indeed, endogenous and exogenous HGF prevents acute hepatic failure in rodents, associated with the anti-apoptotic and anti-necrotic effect of HGF on hepatocytes." (PMID 22536224, 2012). "The clinical significance of serum HGF levels has been assessed in acute hepatic failure and chronic liver diseases." (PMID 23516586, 2013).
adenomyosis (2 papers, 2022 to 2025). The growth of endometrial tissue inside the muscular wall of the uterine corpus. "The termination variant detected in Hepatocyte Growth Factor Activator (HGFAC) highlights it as a plausible candidate gene for adenomyosis, given its role in activating HGF, which in turn promotes epithelial–mesenchymal transition (EMT) and drives glandular invagination into the myometrium." (PMID 41374450, 2025). "As a mechanistic basis of gland invagination, we investigated the role of HGF, either alone or in combination with estrogen, in the occurrence of epithelial-mesenchymal transition (EMT) in adenomyosis." (PMID 35887822, 2022). "A line of evidence demonstrated that estrogen and estromedin (estrogen-regulated) growth factor, such as HGF-induced EMT of epithelial cells, may be involved in the development of adenomyosis or may contribute to the metastatic potential of cancer cells." (PMID 35887822, 2022).
airway hyperresponsiveness (2 papers, 2012 to 2021). "Mesenchymal stem cell–secreted HGF contributed to the conversion of fully differentiated Th17 cells into functional T regulatory (Treg) cells; however, HGF decreased the levels of Th2 cytokines (IL-4, IL-5, and IL-13) in bronchoalveolar lavage fluid and attenuated airway hyperresponsiveness." (PMID 34421795, 2021).
alcohol (2 papers, 2021 to 2024). "A further analysis of four patients with alcohol-related HCC, identified LOH in CDKN2A and CMM loci (involved in overexpression of HGF) in three patients." (PMID 33572904, 2021).
alcohol abuse (2 papers, 2015 to 2024). The use of alcoholic beverages to excess, either on individual occasions ("binge drinking") or as a regular practice.
alcoholic liver cirrhosis (2 papers, 2015 to 2020). A disorder of the liver characterized by the presence of fibrotic scar tissue instead of healthy liver tissue. "In the study, concentrations of HGF, IL-1α, and IL-6 were analyzed in patients with alcoholic liver cirrhosis classified according to the Child-Pugh scoring system." (PMID 26448742, 2015). "Concentrations of HGF, IL-1α, and IL-6 increase with severity of alcoholic liver cirrhosis, and the concentration of HGF increases with an increase in proinflammatory cytokines concentration." (PMID 26448742, 2015). "The aim of the study was to evaluate concentrations of HGF protein and proinflammatory cytokines IL-1α and IL-6 in serum of patients with different stages of alcoholic liver cirrhosis." (PMID 26448742, 2015). "The highest HGF concentrations were observed in patients with class C alcoholic liver cirrhosis." (PMID 26448742, 2015). "The concentration of HGF can be a marker of severity of alcoholic liver cirrhosis." (PMID 26448742, 2015). "According to our best knowledge, relationship between serum concentrations of HGF and serum concentrations of the proinflammatory cytokines (Il-1α, Il-6) in patients with alcoholic cirrhosis has not been described yet." (PMID 26448742, 2015).